LRIG1 (leucine rich repeats and immunoglobulin like domains 1)
Diseases named in the same sentence as LRIG1 in open-access papers (continued):
Sharing a sentence is not in itself a finding about the gene and the disease.
melanoma (10 papers, 2018 to 2024). A malignant, usually aggressive tumor composed of atypical, neoplastic melanocytes. "ESCs at the basal layer of the epidermis mostly differentiate into other epidermal cells They express high levels of α6 and β1 integrins, melanoma-associated chondroitin sulfate proteoglycan, and Leu-rich repeats and immunoglobulin-like domain 1 (LRIG1)." (PMID 39717868, 2024). "In vitro study shows isoliquiritigenin interaction with gamma-aminobutyric acid type-B receptor subunit 1 and targeting of miR-301b/LRIG1 signaling pathways causes suppression of melanoma growth." (PMID 36985568, 2023). "The loss of LRIG1 in A375 melanoma cells resulted in decreased expression of ERBB receptors upon EGF stimulation and decreased activation of ERBB3." (PMID 33786987, 2021). "We next investigated the mechanism underlying hypoxia-induced aggressive potential of melanoma cells, and confirmed a dramatic down-regulation of LRIG1 in melanoma cells upon hypoxia." (PMID 30487162, 2019). "To clarify the mechanism underlying the roles of LRIG1 in hypoxia-induced aggressive potential of melanoma cells, we explored the effects of LRIG1 on EGFR/ERK signaling." (PMID 30487162, 2019). "In summary, our research firstly demonstrated that the inhibitory effect of ISL exerted on melanoma proliferation and apoptosis was mediated by miR-301b, underlying which LRIG1 is the potential target of this process." (PMID 30081934, 2018). "A high number of nevi is a known risk factor for the development of malignant melanomas which may reflect a potential oncogenic function of LRIG1 in the skin." (PMID 33786987, 2021). "Here we report that advanced staged, triple wild-type melanoma patients have a survival benefit from high LRIG1 expression." (PMID 33947959, 2021). "In metastasized melanoma patients, LRIG1 expression in metastases predicts survival when EGFR levels are high and in the triple wild-type subtype." (PMID 33947959, 2021). "Next, we immunohistochemically stained LRIG1 in normal skin, nevi, primary melanoma, and metastases." (PMID 33947959, 2021). "In conclusion, our study demonstrated that LRIG1‐TG mice develop melanocytic skin tumors during chemical skin carcinogenesis and a deletion of LRIG1 in human melanoma cells reduces EGFR and ERBB3 expression after EGF stimulation." (PMID 33786987, 2021). "Negative regulation of EGFR by LRIG1 has been reported in glioblastoma multiforme and in melanoma upon hypoxia." (PMID 33947959, 2021). "LRIG1 transcript levels were significantly reduced, both in melanocytic nevi compared to normal skin and during malignant transformation from nevi to melanoma." (PMID 33947959, 2021). "BRAF inhibitor-resistant melanoma cells are sensitive to recombinant LRIG1, which should be further explored as a potential therapy to combat BRAF inhibitor-resistance." (PMID 33947959, 2021). "Both LRIG1 antibodies consistently stained nevus-, primary melanoma-, and metastatic melanoma cells." (PMID 33947959, 2021). "In contrast, it was reported that an overexpression of LRIG1 decreased hypoxia‐induced invasion, migration, and vasculogenic mimicry in human A2058 melanoma cells, thus acting as a tumor suppressor." (PMID 33786987, 2021). "The current study shows that LRIG1 expression is associated with survival in an EGFR-dependent manner and that the association is lost in melanoma subtypes characterized activating mutations downstream of EGFR." (PMID 33947959, 2021). "LRIG1 influences mouse skin carcinogenesis and plays a role in the development of human cSCC and melanoma, where LRIG1 expression appears to be a prognostic factor for a good prognosis." (PMID 33786987, 2021). "Together, our results show that sma-10/LRIG is a conserved regulator of RTK signaling, add to our understanding of LRIG1 in melanoma and identifies recombinant LRIG1 as a potential therapeutic against BRAF inhibitor-resistant melanoma." (PMID 33947959, 2021).
melanoma (continued). "Here, we aim to determine the role of LRIG1 in melanoma tumorigenesis, RTK signaling, and BRAF inhibitor resistance." (PMID 33947959, 2021). "In melanoma patients, the survival benefit from LRIG1 depends on EGFR levels and is lost in BRAF and RAS mutant subtypes." (PMID 33947959, 2021). "To investigate if the same was true in melanoma cells, we generated LRIG1 knockout cells from the melanoma cell line A375 and screened for altered levels of phosphorylated RTKs using antibody arrays." (PMID 33947959, 2021). "LRIG1 is often regarded as a tumor suppressor in several tumors, including cervical cancer, melanoma, and cutaneous squamous cell carcinoma." (PMID 35284334, 2021). "Six melanoma samples displayed a high LRIG1 protein expression and only one sample showed a medium LRIG1 protein expression." (PMID 33786987, 2021). "To test the clinical relevance of LRIG1 in melanoma we first retrieved a dataset from the Gene Expression Omnibus containing microarray expression data from normal skin, benign nevi, and melanoma." (PMID 33947959, 2021). "Immunohistochemical labeling showed that LRIG1 is expressed in malignant melanoma as well as in cSCC." (PMID 33786987, 2021). "As A375 melanoma cells revealed high intrinsic LRIG1 expression, we deleted LRIG1 via CRISPR/Cas9‐mediated gene editing to investigate its function in A375 cells and its influences on the ERBB receptor network." (PMID 33786987, 2021). "LRIG1 is a transmembrane protein that functions as a tumor suppressor and a prognostic marker in many tumor types, including melanoma." (PMID 33947959, 2021). "To elucidate how LRIG1 involved in hypoxia-triggered metastatic potential of melanoma cells, we explored the effects of LRIG1 on EMT." (PMID 30487162, 2019). "Collectively, the present study first confirmed down-regulation of LRIG1 in hypoxia-treated melanoma cells." (PMID 30487162, 2019). "Emerging evidence has substantiated that low expression of LRIG1 correlates with poor survival in patients with melanoma." (PMID 30487162, 2019). "To explore the role of LRIG1 in the development of melanoma responding to hypoxia environment, we investigated the effects of LRIG1 overexpression or silencing on the metastatic potential of melanoma cells." (PMID 30487162, 2019). "The present study thus aimed to explore the role of LRIG1 in hypoxia-induced aggressive invasion, migration, and VM in melanoma cells." (PMID 30487162, 2019). "We therefore further elucidated the function of LRIG1 in hypoxia-induced VM of melanoma cells by establishing a 3D culture model." (PMID 30487162, 2019). "LRIG1 is frequently decreased and often correlated with poor outcomes in various cancers, including melanoma." (PMID 30487162, 2019). "Taken together, these results manifested that miR-301b mediates the anti-cancer effect of ISL on melanoma by functionally targeting LRIG1." (PMID 30081934, 2018). "Next, we confirmed that miR-301b attenuated the anti-cancer effect of ISL on melanoma in vivo and in vitro by functionally targeting LRIG1." (PMID 30081934, 2018). "To validate the therapeutic effect of si-LRIG1 on melanoma, we constructed the xenografted tumor mouse model." (PMID 30081934, 2018). "The results above revealed that the therapeutic effect of ISL on melanoma was impaired when the expression of LRIG1 was downregulated." (PMID 30081934, 2018). "Our data demonstrated that LRIG1 is a potential modulator in anti-cancer activity of ISL against melanoma, as specific knockdown of LRIG1 decreased cell apoptosis exerted by ISL." (PMID 30081934, 2018). "Additionally, the deletion of LRIG1 in human melanoma cells led to the downregulation of the ERBB receptor network and uncovered LRIG1 as a potential oncogene in melanoma." (PMID 33786987, 2021). "Thus, the present study revealed a new tumorigenic function of LRIG1 during mouse epidermal carcinogenesis as well as potentially in human keratinocytes and more particularly in melanoma cells." (PMID 33786987, 2021).
melanoma (continued). "Two other studies in mice showed that LRIG1 can suppress both melanoma tumor growth and invasion." (PMID 33947959, 2021). "Additionally, we analyzed LRIG1 expression in human tissue samples of healthy individuals and patients with cSCC or malignant melanoma by immunohistochemistry." (PMID 33786987, 2021). "In summary, LRIG1 is a conserved regulator of EGFR signaling that is negatively regulated during early melanoma development and that associates with survival in an EGFR-dependent manner at the metastatic stage." (PMID 33947959, 2021). "Additionally, we detected LRIG1 expression in human cutaneous squamous cell carcinoma and melanoma samples." (PMID 33786987, 2021). "Thus, the deletion of LRIG1 showed intriguing effects on ERBB receptors in A375 melanoma cells, considerably decreasing ERBB receptor expression." (PMID 33786987, 2021). "We have shown that LRIG1 is a conserved EGFR regulator that is lost in early melanoma development." (PMID 33947959, 2021). "We speculate that recombinant LRIG1 may suppress proliferation by inhibiting RTK-dependent activation of the PI3K-AKT signaling pathway in vemurafenib-resistant melanoma cells." (PMID 33947959, 2021). "Here, we find that LRIG1 is downregulated during early melanoma development." (PMID 33947959, 2021). "In human tissue, both nevi cells and melanoma cells showed cytoplasmic LRIG1 immunoreactivity." (PMID 33947959, 2021). "However, transgenic animals developed remarkable melanocytic nevi induced by cleaved LRIG1, indicating a potential role for LRIG1 in melanoma." (PMID 33786987, 2021). "We detected LRIG1 expression by western blot analysis in different human cell lines of epidermal origin, including HaCaT keratinocytes, cSCC cells, (A431), and various melanoma cell lines (A375, SK‐MEL2, SK‐MEL28)." (PMID 33786987, 2021). "Interestingly, we identified two different LRIG1 isoforms: HaCaT keratinocytes and A431 cSCC cells expressed isoform A of LRIG1, whereas all melanoma cell lines expressed the smaller isoform B." (PMID 33786987, 2021). "Therefore, we depleted LRIG1 in human melanoma cells (A375) by CRISPR/Cas9 technology and found that this caused EGFR and ERBB3 downregulation in A375 LRIG1 knockout cells 6 h following stimulation with EGF." (PMID 33786987, 2021). "Unfortunately, the role of LRIG1 in melanoma remains poorly defined." (PMID 30487162, 2019). "Consequently, these findings corroborate how LRIG1 deteriorates hypoxia-triggered cancer metastasis in solid tumors, supporting a promising therapeutic target for melanoma intervention treatment." (PMID 30487162, 2019). "Together, the EGFR/ERK pathway may be responsible for LRIG1-mediated melanoma cell aggressive metastasis upon hypoxia by regulating cell invasion, migration, and VM via EMT." (PMID 30487162, 2019). "Transfection with the recombinant LRIG1 plasmids enhanced LRIG1 expression in melanoma A2058 cells." (PMID 30487162, 2019). "So, the current data indicate that LRIG1 may account for hypoxia-induced metastasis of melanoma by enhancing cell invasion, migration, and VM via EMT." (PMID 30487162, 2019). "Finally, we notarized that LRIG1 and miR-301b are negatively correlated in human melanoma progression." (PMID 30081934, 2018). "Invalidation of the relationship between LRIG1 and miR-301b suggested that the expression of LRIG1 in melanoma cells declined drastically upon the ectopic expression of miR-301b, and intratumoral expression level of LRIG1 was significantly restored when miR-301b was silenced." (PMID 30081934, 2018). "To investigate whether miR-301b functionally targeted LRIG1 in the inhibition of melanoma, we firstly performed immunohistochemical assay to detect LRIG1 protein in the xenografted tumors." (PMID 30081934, 2018). "ISL may inhibit the proliferation of melanoma cells by suppressing miR-301b and inducing its target LRIG1." (PMID 30081934, 2018).
melanoma (continued). "To investigate if LRIG1 could be correlated to melanoma survival, we extracted a dataset from The Cancer Genome Atlas (TCGA) containing clinical data and RNAseq data from primary and metastasized melanoma tumors." (PMID 33947959, 2021). "Additionally, erlotinib also antagonized LRIG1 knockdown-induced decrease in E-cadherin and increase in vimentin in hypoxia-stimulated melanoma cells, indicating that LRIG1 depression could enhance hypoxia-induced EMT by activating the EGFR/ERK pathway." (PMID 30487162, 2019). "Leucine-rich repeats and immunoglobulin-like domains 1 (LRIG1) is a pan-negative regulator of receptor tyrosine kinase (RTK) signaling and a tumor suppressor in several cancers, but its involvement in melanoma is largely unexplored." (PMID 33947959, 2021). "We find that LRIG1 is downregulated during early tumorigenesis and that LRIG1 affects activation of the epidermal growth factor receptor (EGFR) in melanoma cells." (PMID 33947959, 2021). "LRIG1 is thought to be a tumor suppressor in non‐small‐cell lung cancer, cervical SCC, and also melanoma and cSCC." (PMID 33786987, 2021). "More importantly, it blocks the EGFR pathway with its antagonist erlotinib abrogated LRIG1 suppression-induced EMT and, subsequently, cell invasion, migration, and vasculogenic mimicry of melanoma cells under hypoxia." (PMID 31703415, 2019). "More important, blocking this pathway with its antagonist erlotinib abrogated LRIG1 suppression-induced EMT, and subsequently cell invasion, migration, and VM of melanoma cells under hypoxia." (PMID 30487162, 2019). "This experimental evidence denoted that LRIG1 is a functional target of miR-301b and mediates the biological behavior of ISL in the treatment of melanoma." (PMID 30081934, 2018). "In this study, we found six mitochondria-related genes, BTG2, CP, LRIG1, CYP1A1, GBP2, and MBNL1, which might be targets of quercetin in melanoma and play crucial roles in melanoma." (PMID 37869567, 2023). "Nuclear LRIG1 was absent in nevus-, primary melanoma-, and metastasis tissues, where LRIG1 instead appeared strictly cytoplasmic with both antibodies." (PMID 33947959, 2021). "In melanoma tissue, the keratinocyte component of the epithelium was reduced and negative for LRIG1." (PMID 33947959, 2021). "Analysis of the melanoma samples obtained from patients shows that LRIG1 is negatively correlated with miR-301b." (PMID 30081934, 2018). "Combining the results of RNA-seq, molecular docking, and bioinformatics analysis, we found six mitochondria-related genes, BTG2, CP, LRIG1, CYP1A1, GBP2, and MBNL1, which might be targets of quercetin in melanoma and provide an available targeting therapy strategy for melanoma." (PMID 37869567, 2023). "Clinically, the expression of LRIG1 in tumor samples obtained from melanoma patients was decreased compared to normal skin samples, while the expression of miR-301b showed the contrary tendency, indicating a negative correlation between LRIG1 and miR-301b." (PMID 30081934, 2018).
bladder cancer (7 papers, 2013 to 2024). "Previous studies have shown that LRIG1 is associated with the progression of many malignant tumors, including bladder carcinoma." (PMID 38454507, 2024). "The results showed that both circLRIG1 and LRIG1 were significantly reduced in bladder carcinoma tissues and cell lines." (PMID 38454507, 2024). "Using a luciferase reporter assay, we confirmed this interaction and found that co-transfection of the wild-type LRIG1 with miR-214-3p mimics in bladder carcinoma cell lines (UMUC3 and T24) reduced the luciferase reporter activity, but not the mutant LRIG1." (PMID 38454507, 2024). "To investigate the role of LRIG1 in bladder carcinoma, we overexpressed LRIG1 in UMUC3 and T24 cells by transfecting them with OE-LRIG1 plasmids, and the Western blot analysis confirmed the elevated protein level of LRIG1." (PMID 38454507, 2024). "To explore the effect of LRIG1 on bladder carcinoma cell metastasis capability, we performed wound healing and Transwell assays." (PMID 38454507, 2024). "We also demonstrated that circLRIG1 functioned as a sponge of miR-214-3p to modulate the expression of LRIG1, and a positive correlation was found between the expression levels of circLRIG1 and LRIG1 in bladder carcinoma tissues." (PMID 38454507, 2024). "We also demonstrated that LRIG1 can serve as a tumor suppressor gene and impair the proliferation and metastasis of bladder carcinoma in vitro." (PMID 38454507, 2024). "circLRIG1 can elevate the expression of LRIG1 by sponging miR-214-3p to repress the tumorigenesis and progression of bladder carcinoma." (PMID 38454507, 2024). "Upregulation of LRIG1 suppresses cell growth and induces cell apoptosis of bladder cancer by inhibiting MAPK and AKT signaling." (PMID 35677536, 2022). "Results from overall survival analysis and disease free analysis with clinical data from TCGA revealed that core mRNAs in the coexpression networks, AHCY, C6orf136 and LRIG1, correlate with the progression and recurrence of bladder cancer significantly." (PMID 32065779, 2020). "Compared with the vector control, the expression of active (cleaved) caspase-8 in the two bladder cancer cells was significantly increased treated with LRIG1 gene." (PMID 24314030, 2013). "And we found that EGFR expression is critical for the effect of LRIG1 on bladder cancer cells in vitro." (PMID 24314030, 2013). "Meanwhile, we overexpressed LRIG1 with adenovirus vector in T24/5637 bladder cancer cell lines, and we used real time-PCR, western blot, and co-immunoprecipitation analysis in order to examine the effects of LRIG1 gene on EGFR." (PMID 24314030, 2013). "All of this changes of biological behavior suggest that LRIG1 is a tumor suppressor gene on aggressive bladder cancer cells." (PMID 24314030, 2013). "The aim of this study was to investigate the impact of LRIG1 on the biological features of aggressive bladder cancer cells and the possible mechanisms of enhanced apoptosis induced by upregulation of LRIG1." (PMID 24314030, 2013). "We found that upregulation of LRIG1 induced cell apoptosis and cell growth inhibition, and further reversed invasion in bladder cancer cell lines in vitro by inhibiting phosphorylation of downstream MAPK and AKT signaling pathway." (PMID 24314030, 2013). "In this study, we attempted to evaluate the inhibitory effects of LRIG1 on aggressive bladder cancer cells." (PMID 24314030, 2013). "With Annexin V-PE staining, early apoptosis was clearly detectable in the two bladder cancer cells treated with transfection of LRIG1." (PMID 24314030, 2013). "Notably, a positive correlation was found between circLRIG1 and LRIG1 expression in bladder carcinoma tissues." (PMID 38454507, 2024). "Moreover, we found the negative correlations between the expression levels of miR-214-3p and circLRIG1 as well as LRIG1 in bladder carcinoma tissues." (PMID 38454507, 2024).